GSK3B (glycogen synthase kinase 3 beta)
Diseases named in the same sentence as GSK3B in open-access papers (continued):
Sharing a sentence is not in itself a finding about the gene and the disease.
gastric cancer (continued). "The constitutive phosphorylation of GSK3β was present in gastric cancer cells and its phosphorylation level was shown to be markedly reduced by ectopic OPCML expression." (PMID 28407749, 2017). "Down-regulation of PI3K/Akt/GSK3β signaling in gastric cancer cells suppresses Wnt5a-induced activation of RhoA and cell migration." (PMID 29213214, 2017). "In many previous studies, gene signatures were ever identified when analyzing expressions in residual gastric cancer cells after neoadjuvant chemotherapy, composing of GSK3B, the β-catenin gene CTNNB1, NOTCH2 and many other genes." (PMID 29088749, 2017). "It has been reported that Akt/GSK-3β signaling suppression reduces β-catenin levels, thereby abrogating gastric cancer cell invasiveness." (PMID 27588482, 2016). "Herein, we found that miR-501-5p repressed GSK3β to activate Wnt/β-Catenin pathway and enhance gastric cancer stem cell phenotype, further suggesting a tumor-repressive role of GSK3β in gastric cancer." (PMID 27846906, 2016). "The present study demonstrated that GSK-3β maintained the epithelial phenotype of BGC-823 gastric cancer cells, and PI3K/Akt-GSK-3β signaling is an upstream factor of ZEB2 activation in the IGF-I-induced EMT process." (PMID 25435948, 2015). "By means of western blotting and IHC techniques, we found that GSK3β protein expression decreased and β-Catenin protein level increased significantly in gastric cancer." (PMID 24335145, 2014). "The overall GSK3β protein level in gastric cancer samples was ∼50% of that in the matched normal samples (n = 8, P < 0.05)." (PMID 24335145, 2014). "To investigate the effects of GSK3β knockdown on gastric cancer phenotype, we transfected control siRNA or GSK3β-specific siRNA into AGS cells." (PMID 24335145, 2014). "In summary, our findings identify a novel role for GSK3β in the regulation of miR-183-96-182 biogenesis through β-Catenin/TCF/LEF-1 pathway in gastric cancer cells." (PMID 24335145, 2014). "GSK3β protein levels are decreased in human gastric cancer tissue compared with surrounding normal gastric tissue, coinciding with increases of β-Catenin protein, miR-96, miR-182, miR-183 and primary miR-183-96-182 cluster (pri-miR-183)." (PMID 24335145, 2014). "Herein, CDH17 knockdown decreased β-catenin and GSK-3β phosphorylation, accompanied by a concomitant increase of Rb and reduction of Cyclin D1 in gastric cancer." (PMID 23554857, 2013). "Our study analysing the expression of CSC related genes in residual gastric cancer cells after neoadjuvant chemotherapy identified a gene signature with a high prognostic impact composed of GSK3B, the β-catenin gene CTNNB1 and NOTCH2." (PMID 22970250, 2012). "In order to determine the role of G17 on GSK3β pathway, Western Blot analysis was performed with G17-treated gastric cancer cells overexpressing the CCK2 receptor (AGSE)." (PMID 20637111, 2010). "In the present study, we performed immunohistochemical tissue array analysis using an antibody against activated form of GSK-3β (pGSK-3β) and found that activated GSK-3β was expressed in 46% human gastric cancer specimens." (PMID 20704706, 2010). "We believe this is the first report on the clinical implication of activated GSK-3β in human gastric cancer." (PMID 20704706, 2010). "The present study analyzed the relationship between GSK-3β activation and cell cycle regulators in gastric cancer specimens." (PMID 20704706, 2010). "In the present study, we found that GSK-3β activation significantly correlated with favorable prognosis in gastric cancer." (PMID 20704706, 2010). "Our studies indicate that inhibition of GSK3β is necessary to activate G17-induced migratory pathways in gastric cancer cells." (PMID 20637111, 2010). "Several recent studies have demonstrated involvement of GSK3β in mediating different pathways in gastric cancer cells, and an inhibition of the kinase following H. pylori infection." (PMID 20637111, 2010).
gastric cancer (continued). "The present study demonstrates that G17-induced migration and MMP7 promoter induction in gastric cancer cells involve an inhibition of GSK3β pathway." (PMID 20637111, 2010). "In the present study, we extended the previous study to evaluate the expression status of active form of phosphorylated active form GSK-3β (pGSK-3β) in 281 surgically excised human gastric carcinoma tissues using immunohistochemical tissue array analysis." (PMID 20704706, 2010). "GSK-3β activation was frequently observed in early-stage gastric carcinoma and was significantly correlated with better prognosis." (PMID 20704706, 2010). "Palonosetron, a 5-HT3 receptor antagonist, inhibited gastric cancer progression by suppressing cell proliferation, migration, and colony formation via induction of G1 cell cycle arrest and promoting autophagy through activation of the GSK3β." (PMID 41155333, 2025). "Furthermore, CLEC-2 has been shown to suppress gastric cancer metastasis by preventing activation of the GSK3B and AKT signaling pathways 10,11." (PMID 41209555, 2025). "The MGST1/AKT/GSK-3β axis tightly regulates ferroptosis in gastric cancer cells." (PMID 38562143, 2024). "AURKA promoted gastric cancer cell growth by regulating GSK-3β." (PMID 38287009, 2024). "Gal-3 antagonizes INF-γ-induced signal transduction via AKT/GSK-3β/SHP2 in gastric cancer cells." (PMID 38022609, 2023). "In our previous researches, we found that CDK5RAP3 can inhibit the phosphorylation of AKT in gastric cancer, thereby inhibiting the GSK-3β mediated phosphorylation, degrading β-catenin and acting as a tumour suppressor in the occurrence and progression of gastric cancer." (PMID 36387125, 2022). "Gsk3β inhibits Wnt/β-catenin signaling by inhibiting AKT in gastric cancer." (PMID 34149925, 2021). "It has been shown that overexpression of miR-27a was associated with high cell proliferation and metastasis in gastric cancer cells through mediating suppression of PH domain and leucine-rich repeat protein phosphatase 2 (PHLPP2) leading to stimulation of the AKT/GSK3B pathway." (PMID 34582667, 2021). "Furthermore, we also found that miR-450a-5p inhibited the activation of AKT/GSK-3β signaling pathway to inhibit the progression of gastric cancer." (PMID 33854971, 2021). "In addition, AKT participated in fatty-acid induced gastric cancer metastasis via the AKT/GSK-3β/β-catenin pathway." (PMID 32226519, 2020). "LMO3 could promote gastric cancer cell invasion and proliferation through Akt-mTOR and Akt-GSK3β signaling pathways." (PMID 32195177, 2020). "In addition, TIPE2 also suppressed the metastasis of gastric cancer cells through the activation of Glycogen synthase kinase 3 beta (GSK3β) and the inhibition of Akt." (PMID 31817720, 2019). "Nevertheless, by identifying the contributing role of β‐catenin, as well as LRP6 and GSK3β, in M hyorhinis‐induced motility, this study may provide valuable evidence for patient‐directed therapies for M hyorhinis‐positive gastric cancer patients." (PMID 31321908, 2019). "Phosphorylated GSK-3β is a negative regulator of the Wnt/β-catenin activation in gastric cancer." (PMID 29335007, 2018). "Importantly, we found that CDK5RAP3 was a significant regulator of GSK3β phosphorylation in gastric cancer, leading to the subsequent degradation of β-catenin and influencing the prognosis of gastric cancer patients." (PMID 29540196, 2018). "Furthermore, GSK-3β inhibitors were utilized to explore the role of Wnt/β-catenin signaling in the suppression effect of cyclin G2 on gastric cancer cell proliferation and migration." (PMID 30547803, 2018). "Interestingly, phosphorylation of GSK3β at Tyr216 was frequently increased and was predictive of better prognosis in early-stage gastric carcinoma." (PMID 29504933, 2018). "OPCML had a tumor-suppressing activity possibly via AKT/GSK3β signaling in gastric cancer." (PMID 28407749, 2017).
gastric cancer (continued). "The results showed that CWP could inhibit the invasion and metastasis of gastric cancer cells through Cox-2/PGE2-PI3K/AKT/GSK3β/β-catenin signal pathway." (PMID 29358963, 2017). "Indeed, different components of the Wnt pathway have been shown to be mutated or dysregulated in gastric cancer, including Wnt1, SFRPs, Axin1 and Axin2, APC, GSK3-β, and β-catenin." (PMID 28230774, 2017). "The influence and mechanisms of GSK3β on miR biogenesis and function in gastric cancer remain unknown." (PMID 24335145, 2014). "Surprisingly, the primary miR-183-96-182 cluster (pri-miR-183) levels were higher in gastric cancer tissues than that in the matched normal tissues, indicating that GSK3β regulates the production of miR-96, miR-182 and miR-183 through β-Catenin at the transcription level." (PMID 24335145, 2014). "We hypothesized that GSK3β regulates miR-183-96-182 cluster through β-Catenin/TCF/LEF-1 pathway in gastric cancer cells." (PMID 24335145, 2014). "We examined whether the decreased expression of β-catenin in Tob1-overexpressing gastric cancer cells could result from the reduced phosphorylation of Akt and GSK3β." (PMID 22710759, 2012). "In addition, a gastric cancer cell line SNU-668 was treated with a GSK-3β inhibitor lithium chloride (LiCl) to examine the correlation between GSK-3β and cyclin D1 expression." (PMID 20704706, 2010). "In addition, gastric cancer cells were cultured and treated with a GSK-3β inhibitor lithium chloride (LiCl) for immunoblot analysis." (PMID 20704706, 2010). "Aberrant regulation of glycogen synthase kinase-3β (GSK-3β) has been implicated in several human cancers; however, it has not been reported in the gastric cancer tissues to date." (PMID 20704706, 2010). "Likewise, AQP3 was reported to promote EMT through the activation of the PI3K/Akt/SNAIL signaling pathway in gastric cancer cells and was found to contribute to stem-like properties, facilitating tumor growth via the Wnt/glycogen synthase kinase-3 beta (GSK-3β)/β-catenin signaling pathway." (PMID 39941100, 2025). "In addition, polysaccharides also inhibit 1-methyl-2-nitro-1-nitrosoguanidine-induced precancerous lesions in gastric cancer rats by downregulating the gene expression of Wnt2β, Gsk3β, PCNA, CyclinD1, and β-catenin by inhibiting the Wnt/β-catenin signaling pathway." (PMID 36144560, 2022). "The Cell Counting Kit-8 (CCK-8) experiment was used to detect the proliferation ability of gastric cancer cells after overexpression or knockdown of miR6778-5p and bioinformatics predicted the relationship between miR6778-5p and glycogen synthase kinase-3β (GSK3β)." (PMID 36210981, 2022). "Thus, the role of GSK-3β in gastric cancer cells still remains inconclusive." (PMID 20704706, 2010). "Thus, our results suggested that GSK-3β activation is lost during the gastric cancer progression." (PMID 20704706, 2010). "But MCM6 supports YAP by activating the PI3K/Akt/GSK-3β signaling pathway, which overactivates YAP and enhances the occurrence and metastasis of gastric cancer." (PMID 40723817, 2025). "In gastric cancer, TNS4 contributes to disease progression by upregulating p-AKT, p-GSK-3β, and β-catenin." (PMID 39995671, 2025). "It suppresses gastric cancer cell proliferation by downregulating ASCT2-mediated glutamine uptake, modulating c-Myc, GSK3β, and AKT phosphorylation, and inducing ROS-mediated apoptosis via Nrf2 suppression, effectively inhibiting in vivo tumor growth." (PMID 40938450, 2025). "A study from 2006 showed that inhibition of GSK3β by SB415286 induced the expression of COX-2 mRNA and protein, as well as its activity in gastric cancer cells." (PMID 40408503, 2025). "There is a regulatory relationship between GSK3β and NRF2 in the context of ferroptosis induction in cisplatin-resistant gastric cancer cells." (PMID 38562143, 2024). "AURKA and GSK3β interact with each other in gastric cancer cells, thereby enabling AURKA to phosphorylate GSK3β at S9, which inhibits its activity." (PMID 39334449, 2024).
gastric cancer (continued). "In summary, the MGST1/AKT/GSK-3β axis modulates ferroptosis by regulating GPX4 levels and activity in gastric cancer cells." (PMID 38562143, 2024). "LncRNA linc00261 bound to both GSK-3β and Slug protein, promoting the degradation of the Slug protein through GSK-3β, thus inhibiting the invasion and metastasis of gastric cancer cells." (PMID 36851033, 2023). "Although a previous study has shown that in gastric cancer cells, RACK1 promotes β-catenin degradation by interacting with GSK3β and stabilizing the β-catenin destruction complex." (PMID 37848434, 2023). "Similar findings were reported in gastric cancer, where HFD or CD36 overexpression was shown to enhance the peritoneal dissemination of gastric cancer cells via the AKT-mediated inactivation of GSK3β and the subsequent stabilization of β-catenin." (PMID 37371076, 2023). "Elgendy and colleagues reported that PPA2 activated the downstream glycogen synthase kinase 3β (GSK3β), which led to the decline of pro-survival protein MCL-1 and mediated metformin-induced gastric cancer cell death." (PMID 37470692, 2023). "Mechanistically, the m6A modification of LHPP mRNA by METTL14 represses its expression; LHPP inhibits the phosphorylation of GSK3b through acetylation and mediates HIF1A to inhibit glycolysis, proliferation, invasion and metastasis of gastric cancer cells." (PMID 35568711, 2022). "CD36 was found to increase the uptake of exogenous palmitic acid in gastric cancer and induce metastasis via the AKT/GSK-3β/β-catenin signaling pathway." (PMID 35785165, 2022). "Collectively, miR-450a-5p repressed gastric cancer cell proliferation, migration and invasion and induced apoptosis through targeting CREB1 by inhibiting AKT/GSK-3β signaling pathway." (PMID 33854971, 2021). "In the human gastric cancer cell line SGC-7901, suppression of PI3K/Akt/GSK3β pathway, and hence, activation of GSK3β inhibited Wnt family member 5A (Wnt5A)-induced activation of RhoA." (PMID 34440861, 2021). "Subsequently, Silencing EME1 in two gastric cancer cell lines decreased the expression of Akt, CCND1, and GSK3B as well as the phosphorylation levels of Akt, CCND1, and GSK3B." (PMID 34719326, 2021). "After a detail investigation of the mechanism, we found that ACTN1 upregulation enhanced the phosphorylation of GSK3β and AKT, as well as, Snail expression levels in gastric cancer." (PMID 34546849, 2021). "The tumour promoting effect of PA via CD36 was reported in gastric cancer cells too, and PA induced metastasis by phosphorylation of protein kinase B (AKT), leading to activation of AKT/ glycogen synthase kinase-3 beta (GSK-3β)/β-catenin signalling pathway." (PMID 32526973, 2020). "TIPE2 expression was lost in AGS, HGC-27, and SGC-7901 gastric cancer cells; gained-expression of TIPE2 suppresses cell migration and invasion in vitro via inhibiting protein kinase B (Akt)/GSK3β/β-catenin signaling." (PMID 33817189, 2019). "Next, we performed wound healing and migration assays and found that GSK3β, LRP6, or Wnt2 knockdown significantly abolished M hyorhinis‐induced gastric cancer cell motility, but the effect of Wnt2 ablation was less robust than that of the other two factors." (PMID 31321908, 2019). "Further studies have shown that UFM1 can inhibit the phosphorylation of AKT and downstream GSK3β by binding to PDK1 and increasing its ubiquitination, thereby inhibiting EMT of gastric cancer cells and exerting a tumor suppressor function." (PMID 31533855, 2019). "The negative regulation of GSK-3β activity by O-GlcNAcylation has been shown in HEK293FT cells and MKN45 gastric cancer cells but appears to be cell type-dependent." (PMID 30853938, 2019). "In gastric cancer, activated AKT induces the in-activation of GSK-3β, thereby activating Wnt/β-catenin signaling." (PMID 29540196, 2018).
gastric cancer (continued). "To further verify the associations among CDK5RAP3, p-GSK-3β (Ser9) and p-AKT (Ser473), we detected the expression of CDK5RAP3, p-GSK-3β (Ser9) and p-AKT (Ser473) in the 209 gastric cancer samples using IHC." (PMID 29540196, 2018). "In gastric cancer cells, down-regulation of PI3K/Akt/GSK3β signaling in SGC-7901 cells suppressed Wnt5a-induced activation of RhoA." (PMID 28289332, 2017). "In our study, in order to clarify the mechanism of CWP inhibiting gastric cancer, we observed the effect of CWP on gastric cancer based on PI3K/AKT/GSK3β/β-catenin signaling pathway." (PMID 29358963, 2017). "On the contrary, PI3K/AKT inhibitor LY294002 can inhibit the invasion of gastric cancer cells and migration, which contributes to downexpression of p-AKT, p-GSK3β, and β-catenin in the cytoplasm and nucleus." (PMID 29358963, 2017). "In this study, we have performed experiments of CWP inhibiting invasion and metastasis of gastric cancer both in vivo and in vitro and revealed the role of Cox-2/PGE2-PI3K/AKT/GSK3β/β-catenin signaling pathway in the process." (PMID 29358963, 2017). "Experimental data demonstrates that Cox-2/PGE2 can activate the PI3K/AKT/GSK3β/β-catenin pathway and CWP can inhibit the invasion and metastasis of gastric cancer by downregulating expression of Cox-2/PGE2." (PMID 29358963, 2017). "Paradoxically, miR-940 has been demonstrated to promote tumor cell invasion and metastasis by downregulating GSK3β/sFRP1 and ZNF24 in gastric cancer, respectively." (PMID 28423620, 2017). "We also reported that galectin-3 interacts with GSK-3b and then regulates WNT signaling to promote gastric cancer motility." (PMID 27626163, 2016). "This study investigated the potential role of galectin-3, which acts upstream of AKT/GSK-3β/SHP2, in gastric cancer cells." (PMID 26934444, 2016). "In conclusion, our study has revealed that miR-501-5p upregulation plays an important role in gastric cancer progression and miR-501-5p is a critical activator of Wnt/ β-catenin signaling by targeting DKK1, NKD1 and GSK3β." (PMID 27846906, 2016). "Collectively, our results suggest that miR-501-5p activates wnt/β-catenin signaling to enhance stem cell-like phenotype in gastric cancer by directly targeting DKK1, NKD1 and GSK3β." (PMID 27846906, 2016). "In the present study, we investigated the crosstalk of galectin-3 with AKT/GSK-3β signaling and IFN-γ resistance in gastric cancer cells." (PMID 26934444, 2016). "Herein, we demonstrated that miR-501-5p was substantially overexpressed in gastric cancer and induced hyper-activation of β-catenin/TCF via directly targeting DKK1, NKD1 and GSK3β." (PMID 27846906, 2016). "However, the specific effects of GSK-3β in IGF-I-induced gastric cancer EMT remain unclear." (PMID 25435948, 2015). "Here we report that inhibition of GSK3β increases nuclear translocation of β-Catenin, which forms a complex with TCF/LEF-1 to enhance miR-183-96-182 cluster gene expression in gastric cancer cells." (PMID 24335145, 2014). "In this study, we found that miR-183-96-182 cluster inhibitors decrease the proliferation and migration of gastric cancer AGS cells and provide a functional link between GSK3β, the miRNA-183-96-182 cluster and the β-Catenin/TCF/LEF-1 pathway in gastric cancer." (PMID 24335145, 2014). "Increase in GSK-3β (Ser9) phosphorylation was detected after IGF-I stimulation for 3 min in both MGC-803 and SGC-7901 gastric cancer cell lines." (PMID 24885194, 2014). "Thus, GSK3β could be a useful prognostic marker for gastric carcinoma." (PMID 25003395, 2014). "Wnt5a dose-dependently stimulates the migration of human gastric carcinoma cells by enhancing phosphorylation of PI3K/Akt and GSK3β and by activating RhoA." (PMID 25003395, 2014). "However, CLEC-2 has been shown to exert tumor-suppressive effects in gastric cancer by inhibiting signaling pathways such as AKT and glycogen synthase kinase-3 beta, thereby reducing tumor invasiveness 10,11." (PMID 41209555, 2025).